TPM2 (tropomyosin 2)
Diseases named in the same sentence as TPM2 in open-access papers (continued):
Sharing a sentence is not in itself a finding about the gene and the disease.
glioma (2 papers, 2022 to 2025). A benign or malignant brain and spinal cord tumor that arises from glial cells (astrocytes, oligodendrocytes, ependymal cells). "TLN1 and TPM2 are key regulators of cytoskeletal dynamics and cell-matrix interactions, directly promoting glioma cell migration and invasion." (PMID 40365337, 2025). "In this study, it was found that TPM1, TPM3, and TPM4 were significantly upregulated in gliomas, while a high expression level of TPM2, TPM3, and TPM4 was significantly correlated with poorer prognosis." (PMID 35892971, 2022). "Interestingly, the univariate Cox regression analyses indicated that a high expression of TPM2/3/4 was a promoting factor for poorer survival of glioma, while the multivariate Cox regression analyses indicated that a high expression of TPM3 was an independent prognosis factor for poor prognosis." (PMID 35892971, 2022). "The results showed that TPM1, TPM3, and TPM4 were significantly more highly expressed in glioma in comparison to normal tissues, while TPM2 mRNA expression showed no statistical differences." (PMID 35892971, 2022). "The results showed that TPM2, TPM3, and TPM4 were more expressed in high-grade gliomas than in low-grade gliomas, while for TPM1, the trend was not as evident as in other groups." (PMID 35892971, 2022).
leiomyosarcoma (2 papers, 2007 to 2013). An uncommon, aggressive malignant smooth muscle neoplasm, usually occurring in post-menopausal women. "Finally, we confirmed the expected overexpression of some genes: KIT and ANO1/DOG1 in GISTs, MDM2 and CDK4 in non-myxoid/round cells liposarcomas, CALD1 and tropomyosin genes (TPM1, TPM2) in leiomyosarcomas, PDGFB in DFSPs, MUC1/EMA in synovial sarcomas, and CD34 in SFTs." (PMID 23734203, 2013).
oral cancer (2 papers, 2014 to 2017). "The rationale of choosing these CNA associated genes was basically due to LRP12, TPM2, EGFR, CCND1 being matched with ICGC and TCGA databases whereas FSCN1, CLPTM1L, CHL1 and CSMD1 had been found to be associated with oral cancer." (PMID 28384287, 2017). "This genetic signature marker contains LRP12, CCND1, EGFR and TPM2 genes that could predict clinical outcomes and facilitate selection of therapeutic strategies in oral cancer management that are tailor-made for patients." (PMID 28384287, 2017).
prostate tumors (2 papers, 2020 to 2022). "Studies have shown that high‐grade, recurrent, and metastatic prostate tumors express lower TPM2 than intermediate, nonrecurrent, and primary prostate tumors." (PMID 35971319, 2022).
adrenocortical carcinoma (1 paper, 2021). "TPM2 has also been found to have potential as a diagnostic marker for patients with adrenocortical carcinoma as well as bladder urothelial carcinoma, and similar findings will provide guidance to researchers." (PMID 34113575, 2021).
deafness (1 paper, 2024). An inherited or acquired condition characterized by the complete loss of the ability to hear from one or both ears. "Among the overlapped DEGs and ASGs, we found two and one hearing loss/deafness genes in R. affinis himalayanus (MMP9 and MPO) and R. sinicus (TPM2), respectively." (PMID 38672325, 2024).
dysplasia (1 paper, 2025). A usually neoplastic transformation of the cell, associated with altered architectural tissue patterns. "When we examined differential gene expression across these clonal populations, we identified a distinct transcriptional signature in the dysplasia origin clone, with several genes including TPM2, FAU, PCBD1, and APCDD1 showing consistent upregulation." (PMID 41360789, 2025).
endometrial adenocarcinoma (1 paper, 2022). "After MDGA1 was removed, the remaining candidate hub genes (RECK, CFL2, TGFBR3, TPM2, and C10ORF91) affecting the survival rate of endometrial adenocarcinoma in the MEbrown module and MEturquoise module were selected." (PMID 35123404, 2022).
endometrial cancer (1 paper, 2012). Primary or metastatic malignant neoplasm involving the endometrium (mucous membrane that lines the endometrial cavity). "Among the proteins linked to proliferation and invasion of endometrial cancer, we identified HSPA1, TPM2, PDIA, ENO and HNRNPK." (PMID 22415234, 2012).
esophageal cancer (1 paper, 2021). A primary or metastatic malignant neoplasm involving the esophagus. "In addition, low expression of Tpm2 was also associated with an unfavorable prognosis in prostate and esophageal cancer patients." (PMID 33628783, 2021).
Fibroadenoma (1 paper, 1996). A benign tumor of the breast characterized by the presence of stromal and epithelial elements. "The levels of tropomyosin 2 and 3 were lower in carcinomas than in fibroadenomas." (PMID 8932346, 1996).
hereditary cardiomyopathy (1 paper, 2021). "These genes include VCP, COL6A2, SYNE2, PYGM gene, and TPM2, and they warrant investigation of the more complex interacting mechanism underlying the hereditary cardiomyopathy phenotypic features." (PMID 33567613, 2021).
liver disease (1 paper, 2024). "Some of the PBMC proteins have been previously connected to liver disease including FSTL1, TSP1, CCL5, and TPM2." (PMID 38335183, 2024).
nuclear cataract (1 paper, 2023). A cataract (disease) that involves the lens nucleus. "Another study found that the expression of TPM2 is higher in lenses from humans with severe nuclear cataract, than in lenses from people with milder forms of the disease." (PMID 37118843, 2023).
osteosarcoma (1 paper, 2025). A usually aggressive malignant bone-forming mesenchymal neoplasm, predominantly affecting adolescents and young adults. "At the cellular level, overexpression of Tpm2 isoforms reduced co-localization of fascin with actin in the highly aggressive, metastatic SAOS-2 LM5 osteosarcoma cell line." (PMID 40887664, 2025).
ovarian tumor (1 paper, 2011). "Of note, Marcks and Tpm2 were downregulated by 10- and 23-fold respectively in aggressive ovarian tumor cells compared to normal OSE." (PMID 21390237, 2011).
retinal degeneration (1 paper, 2021). Degeneration of the retina. "Three genes (Tpm2, Myh11, Tagln) may be related to cellular filaments, and Mdk (midkine) and C2 (complement C2) are connected to retinal degeneration and AMD, respectively." (PMID 34404875, 2021).
Sepsis (1 paper, 2019). Sepsis is defined as life-threatening organ dysfunction caused by a dysregulated host response to infection. "Tpm1, Tpm2, and Tpm3 mRNA levels decreased in the TA after 24 and 48 h of sepsis." (PMID 31660704, 2019). "Tpm1, Tpm2, and Tpm3 mRNA levels decreased in the DIA after 48 h of sepsis." (PMID 31660704, 2019).
Stroke (1 paper, 2025). Sudden impairment of blood flow to a part of the brain due to occlusion or rupture of an artery to the brain. "Six days post-stroke, differentially expressed thin filament proteins were annotated as follows: Ablim1, Pdlim1, Lmod2, Dbnl, Parvb, Pdlim3, Tpm2, parvin alpha (Parva), and destrin (Dstn) were upregulated, while Lmod3 was downregulated." (PMID 41226396, 2025).
synucleinopathy (1 paper, 2025). A neurodegenerative disease that is characterized by the abnormal accumulation of aggregates of alpha-synuclein protein in neurons, nerve fibers or glial cells. "Instead, we demonstrated the suppression of other microglial mobility/phagocytosis-associated genes such as Icam2, Acta2, Fos, Fosb, Egr1, Lamb2 and Tpm2 in both synucleinopathy patients and the animal model." (PMID 41258081, 2025).
Type 2 diabetes (1 paper, 2016). "Protein isoform Tm1, encoded by TPM2, has an important function in cancer development and metastasis and we have shown that TPM2 expression is increased in Type 2 diabetes and by elevated insulin levels (unpublished)." (PMID 27649540, 2016).
tumor (39 papers, 2009 to 2025). "Most functional data stem from studies on other epithelial cancers, where TPM1 and TPM2 have been implicated as tumor suppressors." (PMID 40937226, 2025). "The tumor suppressor effect of TPM2 was associated with blocking YAP1 nuclear translocation and thus leading to its inactivation." (PMID 36823643, 2023). "TPM2 loss is associated with Ras homolog gene family member A (RhoA) activation and tumor proliferation and transfer." (PMID 31487691, 2019). "Next, YAP1 overexpression was tested to see if it could reverse the tumor suppression caused by TPM2." (PMID 36823643, 2023). "Analysis of the primary BL specimens showed cytoplasmic TPM2 expression in the tumor cells of 8/11 (73%) NR but only 5/36 (14%) R patients, showing a significant association between this marker and resistance to therapy (p = 0.0002 by Fisher Exact test)." (PMID 39424708, 2025). "Mechanistically, in co-culture with tumor cells, downregulation of TPM2 on tumor cells increases neutrophil elastase (ELANE) levels in neutrophils regulated by p38/ MAPK signaling activation, and ELANE promotes tumor cell progression through the Hippo pathway." (PMID 40199876, 2025). "In the “positive” cases, TPM2 was expressed in the large majority of tumor cells with a signal intensity varying from weak to strong across cases." (PMID 39424708, 2025). "In order to confirm expression in the tumor cells, we tested TPM2 protein by IHC in 47 BL patients (10 of which were analyzed also by sc-RNAseq and/or qRT-PCR) using diagnostic tissue samples collected at multiple Institutions in Europe, USA, and Canada." (PMID 39424708, 2025). "The reduced expression of TPM2 in PCa patient tumor tissues is significantly correlated with a less favorable prognosis, suggesting that downregulation of TPM2 predicts poor outcomes for PCa patients." (PMID 39055653, 2024). "It was found that YAP1 overexpression partially reversed the tumor-inhibiting effect of TPM2 overexpression." (PMID 36823643, 2023). "TPM2 was found to be severely downregulated in tumor tissues of PCa patients compared with tumor-adjacent normal tissues." (PMID 36823643, 2023). "PC-3 cells were inoculated in the armpit of BALB/c nude mice, and TPM2 overexpression was found to significantly delay tumor growth." (PMID 36823643, 2023). "It has been demonstrated that TASC overexpressing CNN1 and TPM2 at the protein level indeed directly supports cancer progression by enhancing the proliferation, migration, and metastatic potential of tumor cells." (PMID 37686101, 2023). "By subcutaneous tumor analysis, we found that overexpression of TPM2 suppressed the expression level of YAP1, especially the staining abundance in the nucleus." (PMID 36823643, 2023). "Invasion and metastasis are major hallmarks of tumor progression, and overexpression of TPM2 accordingly inhibited the migration and invasion of C4-2B and PC-3 cells." (PMID 36823643, 2023). "In summary, five candidate genes (TIMP1, SPARCL1, MYL9, TPM2, and CNN1) were finally characterized as the hub gene associated with tumor recurrence in CRC." (PMID 33897765, 2021). "It has been reported that TPM2 was found to be downregulated in CRC, and TPM2 loss was related with RhoA activation and tumor proliferation in CRC." (PMID 30446877, 2019). "Compared to paired adjacent normal tissues, tumor samples had statistically low TPM2 mRNA levels." (PMID 36823643, 2023). "The effect of TPM2 on PCa progression was assessed in vitro and in vivo by quantifying proliferation, migration, invasion and tumor growth assays, and the mechanism of TPM2 in PCa progression was gradually revealed by Western blotting, immunoprecipitation, and immunofluorescence staining arrays." (PMID 36823643, 2023). "The study of TPM2 as a biomarker of tumor tissue is also one of the hot research topics." (PMID 37686101, 2023). "Moreover, subcutaneous tumor analysis revealed that Ki67 staining abundance was significantly reduced with TPM2 overexpression." (PMID 36823643, 2023).
tumor (continued). "Interestingly, TPM2 was recently found to be a tumor suppressor gene whose expression is down-regulated in breast cancer." (PMID 34732768, 2021). "Moreover, the tumor microenvironment—including stromal and immune components—can influence TPM2 levels and activity, and genetic alterations such as copy number variations may further modulate its expression and function." (PMID 41127012, 2025). "Additionally, while lower in global rankings, several genes including COL6A3 (extracellular matrix remodeling), FKBP5 (glucocorticoid signaling), IGFBP2 (tumor invasion and angiogenesis), and TPM2 (cytoskeletal stability) appeared prominently in local SHAP plots for specific cancer samples." (PMID 40941703, 2025). "Moreover, the increased expression of related genes, such as TPM2, raises the hypothesis that this may influence the interaction between tumor cells and the extracellular matrix, as well as the remodeling of the cytoskeleton." (PMID 41127012, 2025). "Moreover, the expression levels of MYL9 and TPM2, but not MSN were significantly associated with the advanced TNM stage, implying that MYL9 and TPM2 may play a key role in tumor progression, and predicted a worse outcome in CRC." (PMID 37031206, 2023). "Therefore, we speculate that TPM2 inhibits tumor development by inhibiting the nuclear localization of YAP1, which is common to other cancer types." (PMID 36823643, 2023). "Therefore, TPM2 may also be involved in the process of tumor formation and metastasis via this mechanism." (PMID 31487691, 2019). "Analysis of paired samples with both FFPE tissues and fresh frozen tumors showed that transcript levels of ACTA2, TPM2, CALD1, and TAGLN were significantly and positively correlated with the stromal percentage of the tumor." (PMID 37296997, 2023). "Our results demonstrated that the expression of TPM2 and TPM4 were negatively correlated with tumor purity (p < 0.05) indicating highly expression in HCC microenvironment." (PMID 34850589, 2022). "After intersecting genes in the yellow module of WGCNA with DEGs, we identified five myCAFs marker genes defined by previous single-cell sequencing that were significantly down-regulated in tumor tissues, including ACTA2, MYL9, TAGLN, TPM1, and TPM2." (PMID 35309916, 2022). "In the current study, strong interaction was predicted between TPM2 and myosin light chain 9 (MYL9), which deserves to be further investigated to unveil its potential impact on the tumor recurrence of CRC." (PMID 33897765, 2021). "While some of these proteins such as SNRNP70 and SRSF5 are the components of the spliceosome complex, the others, namely, SORBS1, TPM2 and MYH11 were reported to have a role in tumor metastasis and development 41–43." (PMID 34728699, 2021). "GEPIA database analysis indicated that those hub genes were significantly upregulated in the tumour tissues; however, VCL, TPM2, and TPM1 were significantly downregulated." (PMID 34112125, 2021). "Tumor stage also affects TPM2 expression and its prognostic relevance, and distinct molecular subtypes of CRC may regulate TPM2 through different transcriptional programs." (PMID 41127012, 2025). "Of note, the single TPM2-positive case in the R group (BL101) for which sc-transcriptomics detected TPM2 RNA expression in the tumor cells, indeed displayed TPM2 protein staining in the tumor cells by IHC." (PMID 39424708, 2025). "We propose that increased TPM2 expression enhances cytoskeleton dynamics, altering cellular adhesion to the extracellular matrix (ECM) and modifying tumor cell interactions with the microenvironment, including angiogenesis and immune evasion, thereby increasing migratory and invasive capacities." (PMID 41127012, 2025). "Furthermore, downregulation of TPM2 activates ELANE of neutrophils to facilitate ERK1/2 activation, thus enhancing IL1β and IL8 secretion for chemoattraction of more neutrophils to tumor microenvironment." (PMID 40199876, 2025).
tumor (continued). "In other words, a decrease in HMW TPM1/TPM2 might indicate a more aggressive tumor, but not necessarily bladder-specific." (PMID 40937226, 2025). "Notably, iCAFs marked by TPM2 were enriched in the initial differentiation phase while myCAFs characterized by BIRC3, CCT6A, HNRNPF, and ID1 were enriched in the terminal differentiation phase during tumor progression." (PMID 37968457, 2023). "Although previous studies, such as Cui, reported downregulation of TPM2 in CRC cell lines, these findings were derived from in vitro models and may not fully capture the gene’s behavior in patient-derived tumor tissues." (PMID 41127012, 2025). "In addition, we defined genes being expressed by all three MYC tumor groups, but absent in SHH tumors (e.g., Ogn, Tpm2, and Rarres1)." (PMID 35318328, 2022).